IL6 (interleukin 6)
Diseases named in the same sentence as IL6 in open-access papers (continued):
Sharing a sentence is not in itself a finding about the gene and the disease.
cancer (continued). "The importance of IL-6 on cancer pathobiology has been well recognized from different types of tumors." (PMID 29245982, 2017). "Most importantly, we determined that Dub3 responded to extracellular signals such as IL-6, and that the resultant signaling prevented Snail degradation, and promoted cancer growth, invasion, and migration." (PMID 29147673, 2017). "Some studies have reported that various biomarkers, such as TNF-alpha, interleukin (IL)-1 beta, IL-6, IL-2, CRP, etc., are associated with cancer-related fatigue, although the results of these studies are not consistent in regarding this issue." (PMID 28679410, 2017). "In co-culture systems, MFs secreted high levels of IL-6, while cancer cells produced high levels of TGF-β." (PMID 28819126, 2017). "Activation of IL-6 signaling also promotes oncogenesis, by regulating cancer cell survival, proliferation, apoptosis, angiogenesis, and drug resistance." (PMID 28208810, 2017). "For example, cancer cells stimulate expression of adipokines and adipocytokines (including IL-6, IL-1β, CCL2, CCL5, TNF-α, MCP-1, leptin), proteases, and inhibitors (e.g., MMP-11, PAI-1)." (PMID 28101337, 2017). "Shp2 was reported to be involved in the Ras/Erk1/2 signaling pathway, triggered by IL-6; however, the detailed effect of Shp2 on IL-6 signaling-promoted cancer development and progression, is largely undefined." (PMID 28208810, 2017). "We previously found that cancer-derived IL-6 induces T cell suppression of MDSCs in vitro via the activation of STAT3/IDO signaling pathway." (PMID 29326716, 2017). "Circulating levels of IL-6 have been reported as forecast cytokine of survival and metastasis in human cancers." (PMID 28676747, 2017). "We next investigated the effects of IL-6 blockade on the chemosensitivity of the organoids by evaluating the fluorescence (EGFP) intensity of cancer cells and performing a histological examination of the organoids." (PMID 28951614, 2017). "IL-6 plays important roles in a variety of biologic processes in different types of cells, including the cancer cells." (PMID 28859117, 2017). "The most validated cytokines involved in cancer progression are IL-1, IL-4, IL-6, while IL-2 has been the most understood anti-inflammatory cytokines used to boost the host immunity against cancer." (PMID 28927416, 2017). "The maintenance of an inflammatory TME is further stabilized through the JAK/STAT and the IKK/NF- χβ pathways, whose effects are robustly sustained by a feedback from cancer cells through the production of inflammatory cytokines such as IL-1β, IL-6 and TNF-α." (PMID 28969664, 2017). "In the PTCL model, LIN28B led to upregulation of IL-6, a let-7 microRNA target, and is consistent with earlier work from the Struhl lab that linked molecular inflammation and cancer through a positive feedback loop involving NF-κB, LIN28B, let-7, and IL-6." (PMID 28400788, 2017). "In the MS model, IL-6 triggered Notch activation which contributed to cancer stem cell self renewal, promoted hypoxia survival and sustained aggressive invasive phenotype of the malignant cells." (PMID 28966805, 2017). "There is a growing consensus that plasma IL-6 is a prognostic factor in solid organ malignancies, however changes in plasma IL-6 levels are affected by carcinoma type." (PMID 28384249, 2017). "The interaction between the cancer cells and macrophages is mediated by IL-6 produced under the regulation of HDAC3 translocation to the nucleus in the cancer cells." (PMID 26745602, 2016). "When cancer cells have metastasized to bone, secreted IL-6 and IL-8 can act on neighboring osteoblasts to provoke secretion of RANKL, which in turn can act on macrophages/monocytes to promote their differentiation to osteoclasts." (PMID 27571113, 2016). "Intriguingly, both TNFalpha and in particular IL-6 have been previously shown to promote epithelial ovarian tumorigenesis and cancer progression." (PMID 27527602, 2016).
cancer (continued). "Pharmacological inhibition of IL-6/STAT3 activation by a JAK inhibitor restrained cancer stem cell growth in vitro and inhibited self-renewal in vivo." (PMID 27732936, 2016). "Elevated serum IL-6 levels have been found correlating with poor prognosis of patients with advanced stages of cancer." (PMID 27383632, 2016). "In this study, in an effort to further understand the mechanisms by which ESE3/EHF controls cancer stem-like cells we uncovered that IL-6 is a key target repressed by ESE3/EHF." (PMID 27732936, 2016). "SFN was reported to inhibit IL-6-induced as well as constitutive STAT3 activity in a number of cancer cell lines." (PMID 27304884, 2016). "While several preclinical models of cancer cachexia are available, the ApcMin/+ mouse model of cancer cachexia exhibits chronically elevated plasma IL-6 levels, muscle wasting, and liver metabolic dysfunction." (PMID 27449092, 2016). "The interaction of glycoprotein 130 (gp130) with the cytokines of Interleukin-6 (IL-6) family has proved to play a crucial part in several cancers." (PMID 27917904, 2016). "By treating cancer cells with exogenous IL-6, we confirmed that IL-6 promotes cell invasion by stimulating the STAT3/Bcl-XL pathway." (PMID 26895473, 2016). "Cancer-derived factors that drive the generation of MDSCs in the bone marrow include G-CSF and GM-CSF, various interleukins like IL-6 and IL-1β, prostaglandin E2 (PGE2), tumor necrosis factor-α and VEGF." (PMID 27029037, 2016). "Aberrant IL6 signaling is likewise able to induce a state of chronic inflammation, as observed in many cancer types and inflammatory diseases." (PMID 26889381, 2016). "It has been demonstrated that the adipokines MCP-1 and IL-6 indirectly promote tumorigenesis through infiltrative macrophage inflammation leading to cancer development." (PMID 26794215, 2016). "Cancer-related death was considered as the endpoint, and the optimal cutoff value of serum IL-6 was calculated as 6.3 pg/mL using receiver operating characteristic curve analysis." (PMID 26858756, 2016). "Visceral adipose tissue can release several cytokines as tumor necrosis factor (TNF-α) and interleukin-6 (IL-6) which are considered to form a link between inflammation and cancer." (PMID 27029038, 2016). "Through diverse mechanisms, IL-6 plays important roles in the pathogenesis of inflammatory diseases and cancer." (PMID 27413547, 2016). "IL-6 triggers the DNMT1-mediated hypermethylation at specific promoters in cancer cell lines, that in turn increases the cellular growth rate along with other oncogenic properties." (PMID 27462204, 2016). "Second, the findings from an immunohistochemical examination showed that the cancer cells were positive for IL-6." (PMID 27659803, 2016). "On the other hand, IL-6 has a very important role in development of drug resistance in cancer and correlated with the poor disease-outcome." (PMID 27045798, 2016). "The signaling pathway downstream of IL-6, especially JAK-STAT3 pathway is aberrantly activated and is associated with the cancer progression, though this pathway is an essential component of normal development and homeostasis." (PMID 27825119, 2016). "In the metastatic prostate tumor MYC is downregulated due to STAT3-induced transcriptional suppression, however there are reports indicating that STAT3 can also upregulate MYC in different kinds of cancer through IL6." (PMID 28005952, 2016). "The IL-6/STAT3/NF-κB positive feedback loop links inflammation to cancer and maintains cells at a transformed state." (PMID 27248826, 2016). "High levels of circulating IL-6 are observed in almost all types of cancer and predict a poor outcome." (PMID 27068103, 2016). "Among HIV-positive adults, higher levels of interleukin-6 (IL-6), D-dimer, and high-sensitivity C-reactive protein (hsCRP) are associated with an increased risk of cardiovascular disease (CVD), cancer, and all-cause mortality." (PMID 27171281, 2016).
cancer (continued). "Collectively, the findings presented herein demonstrate that IL-6 in ascites function through membrane-bound IL-6R expressed in cancer cells and increase the EOC cell invasion via JAK2-STAT3 signaling." (PMID 27825119, 2016). "And the existence of DR6 in cancer cells can facilitate the endothelial cells proliferation via IL-6/VEGF-mediated mechanism during tumor angiogenesis." (PMID 26950598, 2016). "Aberrant IL-6/STAT3 signaling in cancer cells have emerged as a major mechanism for cancer initiation and development." (PMID 27938379, 2016). "IL-6 is closely involved in growth and metastasis regulation in cancers as well as in the host immune defense mechanism for foreign pathogens." (PMID 26745884, 2016). "Mast cells play a key role in the pathogenesis of cardiovascular diseasesand cancers via secreting a variety of cytokines includingTNF-α, IL-3, IL-4, IL-5, IL-6, IL-10, IL-13, IL-14 and IL-16." (PMID 26625310, 2016). "Although IL-6 targeting therapies have shown promising outcomes in inflammatory diseases and some types of cancers, safety issues related to IL-6 targeting approaches have been reported." (PMID 26840088, 2016). "Nonetheless, other studies have shown beneficial effects of the blockage of IL-6 and its signaling pathway in the control of skeletal muscle wasting and cachexia progression in several mouse cancer models." (PMID 27330885, 2016). "Cancer-induced inflammation releases increased levels of circulating inflammatory cytokines such as interleukin 6 and TNFα, both of which initiate SIR." (PMID 27632196, 2016). "Positive staining for IL-6 was evident in 51% of the 162 cancer specimens, and a significant positive correlation was found in cancer specimen that expressed PD-L1 and IL-6." (PMID 26761210, 2016). "While these effects were witnessed in cancer cells, it is likely that IL-6 can regulate DNMT1 in other cell types such as brain cells, particularly during development." (PMID 27462204, 2016). "It has been reported that IL-6 is involved in stimulating proliferation in many cancers, such as colorectal cancer, prostate cancer, intestinal disease, and so forth." (PMID 27231908, 2016). "As cancer is basically a disease of tissue growth regulation failure, IL-6 has important roles in the pathophysiology of cancer." (PMID 27153074, 2016). "IL-6 signalling has also been investigated as a potential target for several types of cancer therapies." (PMID 27034885, 2016). "Some recent studies have shown the relationship between cancers and inflammatory factors, such as IL-6 and IL-10." (PMID 27230680, 2016). "The interleukin-6 (IL-6)/JAK/STAT3 signaling pathway has recently been shown to have a central role in inflammation-mediated cancers, such as those of the liver and stomach." (PMID 27049718, 2016). "Inaword, these findings are noteworthy that CUDR plus IL6 links to cancer cells growth in the inflammatory environment." (PMID 27833137, 2016). "The data presented herein not only provide a plausible and convincing explanation for how IL-6 increases MMP-14 in cancer to drive metastasis, but implications of this research can be extended into multiple other fields of study." (PMID 27531896, 2016). "It has been demonstrated that IL-6 is secreted by many types of cancer cells as it occurs in renal cell carcinoma." (PMID 27294919, 2016). "Especially, pro-inflammatory cytokines such as IL-18, TNF-α, and IL-6 have a positive role in cancer progression, including cancer cell migration." (PMID 27589563, 2016). "IL-6 and TNFα are produced by the activated macrophages, a potential mechanism involved in cancer development." (PMID 26951793, 2016). "IL-6 (IL6) cytokine found in toll like receptor signaling pathway has been involved in acute and chronic inflammation and has been associated with cancer progression." (PMID 26892392, 2016).
cancer (continued). "Activation of NF-κB in immune cells results in the expression and production of multiple pro-inflammatory cytokines, including TNFα, IL-1, IL-6, IL-17 and IL-23, which promote cancer development in multiple mouse models." (PMID 31051015, 2016). "The elevated levels of IL-6 frequently detected in cancer patients correlate with a poor prognosis in these patients." (PMID 27080032, 2016). "Fat cells secrete the inflammatory mediators tumor necrosis factor-alpha (TNF-α) and interleukin 6 (IL-6), which promote cancer induction." (PMID 26977321, 2016). "So far, many studies have focused on IL-6 as a player in malignant tumor progression by facilitating epithelial-mesenchymal transition (EMT), inflammation, and angiogenesis." (PMID 27499248, 2016). "In view of the fact that α5β1 inhibition on CD11b+-cells reversed EDA effects on cancer growth in vivo, the changes in iNOS and IL-6 seemed irrelevant in our model." (PMID 27653627, 2016). "IL-6 and IL-8 are among pro-inflammatory cytokines with profound effects on biology of cancer cells." (PMID 27101408, 2016). "In various human cancers malignant cells and host infiltrating cells express and secrete a range of Th1, Th2, and Th17 cytokines (IL-1β, IL-2, IL-4, IL-6, IL-10, IL-17, and IFN-γ) and TGF-β." (PMID 27777963, 2016). "Recently, it has been suggested that targeting for IL-6 mediated signaling is a potential strategy for controlling the systemic inflammatory response, as well as the malignant behavior of cancer cells themselves." (PMID 26812901, 2016). "The current patient demonstrated a poor histological response to preoperative chemoradiotherapy and strong IL-6 expression in the residual cancer cells." (PMID 27316348, 2016). "IL-6 is an activator of Jak2/STAT3 signaling pathway which is involved in the development of cancers and EMT." (PMID 27121055, 2016). "In cancer development, IL-6 promotes proliferation, angiogenesis, migration, invasion, and metastasis." (PMID 26623559, 2016). "Accordingly, we found that IL-6 treatment promoted transformation and cancer stem-like features in normal prostate epithelial cells." (PMID 27732936, 2016). "Immunostaining analyses of the increased E-cadherin and diminished N-cadherin levels confirm that IL-6 upregulates radiation-induced EMT responses in cancer cells." (PMID 27462787, 2016). "We previously showed that increased IL-6 expression in cancer cells predicted a poor response to chemoradiotherapy and an unfavorable prognosis in patients with oral SCC." (PMID 27316348, 2016). "Among the cytokines and chemokines produced by persistent pulmonary inflammation, interleukin-6 (IL-6) plays a pivotal role in promoting cancer development as shown in studies using in vitro and in vivo models of lung carcinogenesis." (PMID 26372664, 2016). "It is significant that in a population of cancer patients with abdominal malignancies, the C-reactive protein, IL-6, nuclear factor-κB, and E-Sel levels in patients with DVT were meaningfully higher than the control group." (PMID 27326361, 2016). "E.coli infection alone produced elevated levels of IL-6 within bladder tissue similar to the levels demonstrated in urinary tract inflammatory diseases and cancer." (PMID 26841926, 2016). "IL-6 is abundant in the serum of 50% of the patients with metastatic renal cell cancer; moreover, these cancer cells have shown the production of IL-6 and expression of IL-6 mRNA and of the soluble and membrane-bound gp120 chain of the IL-6 receptor." (PMID 27294919, 2016). "The PI3K/Akt/mTOR and MAPK/ERK signaling pathways are acknowledged as the main signaling pathways that mediate IL-6's stimulating effect in many cancer types." (PMID 27174914, 2016). "This further supports the clinical relevance of Rho/ROCK signaling in regulating chemoresistance, as IL-6 has been well documented to be a pro-survival cytokine in cancers." (PMID 27213590, 2016).
cancer (continued). "In patients with cancer cachexia, high circulating levels of IL-6 seems to act as mediator of skeletal muscle proteolysis." (PMID 27330885, 2016). "IL-6 is characterized as a COX-2-dependent cytokine necessary to activate numerous oncogenic signals acting downstream of COX-2 in cancer cells via activating STAT3 (signal transducer and activator of transcription 3)." (PMID 27385366, 2016). "By activating downstream Janus kinase (JAK) signal transducer and activator of transcription-3 (STAT3) signaling, IL-6 promotes cancer cell proliferation, survival, and metastatic dissemination." (PMID 27006530, 2016). "Robust pro-inflammatory studies have revealed that IL-6 intermediates the AKT/PI3K pathway in contribution to cancer cell survival, but the connection with MSI1 remain uncertain." (PMID 27285760, 2016). "Recent works have uncovered a mechanism by which, in cancer cells, TGFβ1 signals through NF-kB activation and nuclear translocation, ultimately leading to a rise in IL-6 secretion." (PMID 27851822, 2016). "These combined studies confirm that SL1026 is a potent antagonist of the IL-6 signaling pathway and represents a new class of drug candidate for the treatment of IL-6-mediated diseases including RA, inflammation, and cancer." (PMID 26579954, 2016). "In the tumor microenvironment, IL-6 activates its receptor (IL-6R) on the cancer cell membrane and promotes the development of cancer in the manner of paracrine and autocrine." (PMID 27174914, 2016). "IL-6 is a multifunctional cytokine with central roles in immune and inflammatory reactions, as well as in cancer development." (PMID 27852059, 2016). "Aberrant IL-6–JAK-STAT3 signaling in cancer cells is a major mechanism for cancer initiation, development, and progression." (PMID 27129720, 2016). "The promoter of IL6 contains several SNPs, of which the -174 G>C is the most widely studied for its influence in various cancers." (PMID 27662210, 2016). "It is possible that unwanted biological effects of IL-6, as that occurring in aging and cancer cachexia, are due to its release chronically and at sustainable levels." (PMID 27330885, 2016). "IL-6R trans-signaling pathway is the critical player of IL-6-mediated pathology in autoimmune conditions such as rheumatoid arthritis, colitis, tissue fibrosis and cancer." (PMID 27330885, 2016). "Inflammation is recognized as an enabling characteristic in cancer development and IL-6 is one of several cytokines (IL-1, TNFα, IL-23) found to be essential in inflammatory processes and cancer growth." (PMID 27329584, 2016). "The search for mediators of senescent HPMC activity using specific neutralizing antibodies and recombinant exogenous proteins showed that the intensified angiogenic potential of cancer cells was elicited by IL-6 and TGF-β1." (PMID 26433963, 2016). "On the basis of the pathogenetic role of IL-6 in cancers, a study of the anti-cancer activity of olokizumab appears warranted." (PMID 26840088, 2016). "Another pro-inflammatory mediator with a critical role in muscle wasting during cancer cachexia is interleukin (IL)-6." (PMID 26856534, 2016). "A number of studies have shown that IL-6 modulate cancer stem cell phenotype by regulating nanog expression." (PMID 26919244, 2016). "Clinically, the measurement of IL-1β, IL-18, IL-6, and MIC-1/GDF-15 correlates with the risk of carcinoma and the prognosis of established cancer." (PMID 27429614, 2016). "Taken together, these data suggest the need to consider the differential regulation of not only the MEK and IL-6 pathways, but also other pathways in muscle wasting of cancer cachexia." (PMID 28149280, 2016). "Specifically, loss of ESE3/EHF leads to upregulation of IL-6 and activation of the JAK/STAT3 pathway with consequent induction of EMT and expansion of the cancer stem cell compartment." (PMID 27732936, 2016). "STAT3 can be activated in cancer cells by multiple cytokines and growth factors, best known for IL-6 and its family members." (PMID 31051015, 2016).